PSME1 (proteasome activator subunit 1)
Description:
Implicated in immunoproteasome assembly and required for efficient antigen processing. The PA28 activator complex enhances the generation of class I binding peptides by altering the cleavage pattern of the proteasome.
Synonyms: PA28a; PA28alpha; IFI5111; HEL-S-129m; REGalpha
Tractability: PROTAC: ubiquitination databases record sites on it; its protein half-life has been measured.
Gene: Protein-coding gene on chromosome 14 (24,136,156 to 24,138,967, forward strand). Ensembl gene ENSG00000092010.
Subcellular location (Human Protein Atlas): Cytosol; Nuclear bodies
Pathways (Reactome):
Immune System: Antigen processing: Ub, ATP-independent proteasomal degradation; Cross-presentation of soluble exogenous antigens (endosomes); ER-Phagosome pathway
Metabolism of proteins: Proteasome assembly
Gene Ontology:
Molecular function: protein binding; endopeptidase activator activity
Biological process: regulation of proteasomal protein catabolic process; cellular response to type I interferon; regulation of G1/S transition of mitotic cell cycle; response to oxidative stress
Cellular component: extracellular exosome; proteasome complex; cytoplasm; cytosol; nucleoplasm; proteasome storage granule; proteasome activator complex
Genetic constraint (gnomAD): Loss-of-function variants: 15 observed, 38.95 expected, observed/expected ratio (o/e) 0.39, 90% interval 0.26 to 0.59. The upper end of that interval is the gene's LOEUF score, 0.59, which puts it in group 2 of 6, group 1 being the genes least tolerant of losing a copy. Missense variants: 249 observed, 314.55 expected, observed/expected ratio (o/e) 0.79, 90% interval 0.71 to 0.88. Synonymous variants: 106 observed, 110.42 expected, observed/expected ratio (o/e) 0.96, 90% interval 0.82 to 1.13.
Homologues: Orthologues: macaque PSME1 (99% identical), dog PSME1 (99% identical), guinea pig PSME1 (97% identical), rat Psme1 (96% identical), mouse Psme1 (95% identical), rabbit PSME1 (94% identical), chimpanzee PSME1 (91% identical), pig PSME1 (90% identical), rat Psme1-ps1 (89% identical), tropical clawed frog psme1 (59% identical), zebrafish psme1 (57% identical), Drosophila melanogaster REG (36% identical), and 1 more. Paralogues in human: PSME2 (49% identical), PSME3 (42% identical).
Diseases named in the same sentence as PSME1 in open-access papers:
PSME1 is named in the same sentence as 68 diseases in open-access papers, as found by Europe PMC text mining. Sharing a sentence is not in itself a finding about the gene and the disease. The quoted sentences say what the papers report.
breast carcinoma (7 papers, 2016 to 2025). "Intriguingly, PSME1 was also found to associate with diagnosis or prognosis in other tumor types, e.g. prostate cancer, breast cancer and ovarian cancer." (PMID 27733900, 2016). "To assess whether CP and IP catalytic subunits were co-expressed in breast cancer samples, we performed a principal component analysis (PCA) on gene expression data for CP- and IP-encoding genes and regulatory subunits PA28α and PA28β (encoded by PSME1 and PSME2)." (PMID 27659694, 2016). "Additionally, PSME1/2/3 are implicated in MHC class I molecule-mediated antigen presentation, and their heightened expression is significantly correlated with the staging and prognosis of various tumors, including gastric, colorectal, clear cell renal cell carcinoma, and breast cancer." (PMID 39619148, 2024).
melanoma (7 papers, 2018 to 2024). A malignant, usually aggressive tumor composed of atypical, neoplastic melanocytes. "It has been reported that in oral squamous cell carcinoma (OSCC) and soft tissue leiomyosarcoma, high expression of PA28α in tumor samples corresponds with poor prognosis, while in melanoma, elevated levels of PSME1 were associated with better overall survival." (PMID 34944095, 2021). "Similar to primary melanoma cells, loss of IRF2 dropped the surface expression of MHC I and significantly reduced transcripts of TAP2, ERAP1, and PSME1 detected in B16F0 mouse melanoma cells." (PMID 39281881, 2024). "Related with this, one of the significantly underexpressed proteins was PSME1 (proteasome activator complex subunit 1), which is a regulator of proteasome activity, suggesting that HS treatment inhibits protein degradation in melanoma cells and, in turn, can contribute to modify protein homeostasis." (PMID 29744371, 2018). "Through LASSO regression, the following six genes were specifically identified to have an irreplaceable prognostic effect on melanoma patients: MLKL, PARVA, PKP1, PSME1, RNF114, and TROAP." (PMID 37127623, 2023). "Finally, six LLPS-related genes (MLKL, PARVA, PKP1, PSME1, RNF114, and TROAP) constitute the prognostic model and predicted clinical outcomes in melanoma patients." (PMID 37127623, 2023).
prostate carcinoma (6 papers, 2016 to 2024). A carcinoma that arises from epithelial cells of the prostate gland. "Affinity chromatography followed by MS analysis study reported the high expression of PSME1 correlated with the primary and metastatic phases in prostate cancer." (PMID 37501157, 2023). "For example, increased PSME1 expression was also found in primary and metastatic human prostate cancer and was suggested as a potential target for therapeutic intervention." (PMID 27733900, 2016). "Additionally, several studies have reported that PSME1 is dysregulated in several different cancers, including prostate cancer and oral squamous cell carcinoma (OSCC), suggesting that PSME1 may act as a novel prognostic factor." (PMID 34650966, 2021). "Previous studies have reported that PSME1 is overexpressed in multiple cancers, including ovarian cancer, skin cutaneous melanoma, esophageal squamous cell carcinoma, and prostate cancer, suggesting that PSME1 could be a promising marker and therapeutic target for prostate cancer." (PMID 34650966, 2021).
multiple myeloma (4 papers, 2020 to 2024). "Alternatively, expression of PSME1 was found to be indicative of poor response to proteasome inhibitor treatment in relapsed or refractory multiple myeloma patients." (PMID 34944095, 2021).
ovarian cancer (4 papers, 2016 to 2021). A primary or metastatic malignant neoplasm involving the ovary. "Previous studies also showed that PSME1 could be a molecular signature to discriminate between benign and malignant ovarian tumors, and an early diagnosis and tumor-relapse biomarker." (PMID 27733900, 2016).
lung carcinoma (3 papers, 2022 to 2025). "PSME1, proteasome activator subunit 1, is associated with the production of antigenic peptides presented by MHC I molecules, and its expression level is associated with the treatment response to immune checkpoint inhibitors in patients with lung cancer." (PMID 40299520, 2025).
skin cutaneous melanoma (3 papers, 2021 to 2023). "Similarly, high expression levels of PSME1 were associated with favorable overall survival of skin cutaneous melanoma." (PMID 37501157, 2023).
viral infection (3 papers, 2015 to 2019). "A number of higher expressed proteins are known to be induced by viral infection or interferon signaling (FRIL1 FRIH, VCAM1 and PSME1)." (PMID 31440143, 2019).
colon cancer (2 papers, 2016 to 2017). "Knock-down of PSMA3 (20S proteasomal protein), PSMD3 (19S proteasomal protein), and PSME1 (11S proteasomal protein) resulted in increased size and quantity of FoxM1 compared with control colon cancer cells (brace)." (PMID 28378765, 2017).
COVID-19 (2 papers, 2022 to 2023). A disease caused by infection with severe acute respiratory syndrome coronavirus 2. "Besides, the majority of proteasome subunits studied (unless PSMB9 and PSME1) positively correlated with NLRP3 mRNA expression in COVID-19 patients." (PMID 35327634, 2022). "Our data revealed the upregulation of PSME1 in COVID-19 patients." (PMID 35327634, 2022). "Fifteen proteasomal proteins showed an increase in serum levels of COVID-19 patients, most notably PSMA7, PSME1, PSMB3, PSMA4 and PSMA5, whereas PSMD2 was the only one with decreased levels." (PMID 37739942, 2023).
leiomyosarcoma (2 papers, 2016 to 2018). An uncommon, aggressive malignant smooth muscle neoplasm, usually occurring in post-menopausal women. "In summary, we found elevated expression of the proteasome subunit PSME1 in leiomyosarcomas compared to control tissues, and an association of the expression with increasing histological grade in leiomyosarcoma." (PMID 27733900, 2016). "Moreover, high nuclear expression of PSME1 was significantly associated to poor outcome (overall survival, metastasis-free survival and event-free survival) in leiomyosarcoma patients, although the patient cohort is rather small (n = 34)." (PMID 27733900, 2016). "High expression of proteasome activator complex subunit 1 (PSME1, m/z 9753) in leiomyosarcoma (n = 12), myxofibrosarcoma (n = 13) and undifferentiated pleomorphic sarcoma (n = 12) was associated with poor survival." (PMID 30167993, 2018). "In this study, we used tissue microarrays of soft tissue sarcomas with complex genomes, to evaluate whether PSME1 expression can predict clinical outcome in soft tissue sarcomas, especially leiomyosarcomas." (PMID 27733900, 2016). "Moreover, high nuclear PSME1 expression was found to be an independent predictor of metastasis-free survival in leiomyosarcoma patients." (PMID 27733900, 2016). "Our results suggest that the expression of proteasome subunits such as PSME1 could be taken into account for leiomyosarcoma patients when considering immunotherapeutic strategies in these tumors." (PMID 27733900, 2016).
cardiac arrest (1 paper, 2024). Cessation of breathing and/or cardiac function. "Vitamin B12 may increase the risk of coronary atherosclerosis and cardiovascular death by reducing the levels of VPS29 and PSME1 proteins, while vitamin C may mitigate the risk of cardiac arrest by inhibiting the expression of the TPST2 protein." (PMID 39691718, 2024).
chronic hepatitis (1 paper, 2024). An active inflammatory process affecting the liver for more than six months. "The results showed that the expression of various proteasome-related proteins, especially PSME1, was significantly increased in the sera of patients with chronic hepatitis than in patients with chronic HBV infection, suggesting that PSME1 plays a role in HBV infection in vivo." (PMID 39281837, 2024). "Coincidentally, a recent study showed that the expression of PSME1 in the serum of patients with chronic hepatitis was higher than that in patients with chronic HBV infection, suggesting that PSME1 is involved in HBV infection in vivo." (PMID 39281837, 2024).
coronary atherosclerosis (1 paper, 2024). Atherosclerosis of the coronary vasculature. "Vitamin B12 may increase the risk of coronary atherosclerosis by inhibiting the expression of VPS29 and PSME1 proteins, and elevate the risk of death caused by heart disease through the suppression of PSME1 expression." (PMID 39691718, 2024). "Vitamin B12 may increase the risk of coronary atherosclerosis by inhibiting VPS29 (Mediated Effect=0.031, 95% CI: 0.030–0.032; Mediated Proportion=13.04%, 95% CI: 12.53%-13.56%) and PSME1 (Mediated Effect=0.101, 95% CI: 0.097–0.106; Mediated Proportion=42.75%, 95% CI: 40.88%-44.61%)." (PMID 39691718, 2024).
desminopathies (1 paper, 2013). "A study demonstrated an increased immunoreactivity of the 20S proteasome core as well as its 19S and 11S (synonyms: PA28alpha/beta, PSME1/PSME2) regulators co-localizing with pathological protein aggregates in desminopathies." (PMID 23143191, 2013).
glioma (1 paper, 2024). A benign or malignant brain and spinal cord tumor that arises from glial cells (astrocytes, oligodendrocytes, ependymal cells). "Our findings indicate that Shikonin-induced programed necrosis leads to a downregulation of proteasome activity and a decrease in the expression of immune proteasome subunits PSMB8/9/10 and PSME1/2/3, contributing to the attenuation of stemness in gliomas." (PMID 39619148, 2024).
gouty arthritis (1 paper, 2025). "Additionally, the co-regulatory ceRNA network mediated by circRNA and lncRNA, which upregulates miR550a-5p and miR550a-3-5p, thereby downregulating the expression of PSME1, FERMT3, GRK2, and OS9, can exacerbate gouty arthritis in vitro." (PMID 41311848, 2025).
gynecological cancers (1 paper, 2022). "Interestingly, hierarchical clustering revealed two main clusters of PSM genes, of which one cluster contained five PSM genes (PSMB8-10 and PSME1-2) with high expression in a number of urologic, CNS, and gynecological cancers." (PMID 36123629, 2022).
leukemia (1 paper, 2012). A malignant (clonal) hematologic disorder, involving hematopoietic stem cells and characterized by the presence of primitive or atypical myeloid or lymphoid cells in the bone marrow and the blood. "For the leukemia dataset, among the 10 top-ranked genes, two genes (ZYX and CCND3) are cancer ones, five (APLP2, CD33, SP3, CD63, PSME1) and one other genes (CST3) are directly or indirectly associated with cancer genes, respectively." (PMID 22830977, 2012).
liver cirrhosis (1 paper, 2024). "Additionally, another study reported that PSME1 protein expression in the pathological tissue of patients with liver cirrhosis was higher than in normal individuals." (PMID 39281837, 2024).
myocardial infarction (1 paper, 2024). Gross necrosis of the myocardium, as a result of interruption of the blood supply to the area, as in coronary thrombosis. "Additionally, overexpression of PSME1 has the potential to reduce myocardial collagen deposition, inhibit cardiomyocyte apoptosis, significantly improve cardiac systolic and diastolic functions, and exert a notable effect on preventing cardiac dysfunction after myocardial infarction reperfusion." (PMID 39691718, 2024).
sarcoma (1 paper, 2016). A usually aggressive malignant neoplasm of the soft tissue or bone. "Previous studies on high grade sarcomas using mass spectrometry imaging showed proteasome activator complex subunit 1 (PSME1) to be associated with poor survival in soft tissue sarcoma patients." (PMID 27733900, 2016). "It is of interest that all sarcoma subtypes included in our study expressed PSME1 to a variable extent, while neoadjuvant chemotherapy or treatment with interferon gamma is not standard practice in our hospital." (PMID 27733900, 2016).
Sepsis (1 paper, 2019). Sepsis is defined as life-threatening organ dysfunction caused by a dysregulated host response to infection. "As the immunoproteasome has been shown to be upregulated upon inflammatory conditions, we next investigated immunoproteasome activator PA28 (PSME1) expression in platelets from sepsis patients." (PMID 31783490, 2019). "We observed an upregulation of the immuno-proteasome subunit and activator PA28 (PSME1) in platelets from sepsis patients and increased processing of polyubiquitinated proteins as well as the proteasome substrate Talin-1 under conditions of sepsis." (PMID 31783490, 2019). "Upregulation of the proteasome activator PA28 (PSME1) was assessed by quantitative real-time PCR in platelets from sepsis patients." (PMID 31783490, 2019). "mRNA expression analysis using real-time PCR revealed an upregulation of PA28 (PSME1) in platelets of sepsis patients compared to controls." (PMID 31783490, 2019). "Using real-time PCR we observed upregulation of the proteasome activator PA28 (PSME1) in platelets specifically in the sepsis population in line with increased proteasome activity." (PMID 31783490, 2019).
soft tissue sarcoma (1 paper, 2016). A malignant neoplasm arising from muscle tissue, adipose tissue, blood vessels, fibrous tissue, or other supportive tissues excluding the bones. "In this study, we aimed to validate PSME1 as a prognostic biomarker in an independent and larger series of soft tissue sarcomas by immunohistochemistry." (PMID 27733900, 2016). "Using imaging mass spectrometry we previously identified PSME1 as a prognostic biomarker indicating poor survival in soft tissue sarcoma patients." (PMID 27733900, 2016). "We here show that in soft tissue sarcomas with a complex genome, PSME1 is expressed both in the cytoplasm and in the nucleus." (PMID 27733900, 2016). "Among them, proteasome activator complex subunit 1 (PSME1) was found indicative of poor survival in soft tissue sarcomas." (PMID 27733900, 2016). "To further explore the prognostic value of PSME1 we analysed PSME1 expression in a larger, independent set of soft tissue sarcomas using immunohistochemistry on tissue microarrays." (PMID 27733900, 2016). "We show variable expression of PSME1 in different soft tissue sarcoma subtypes with complex genomes." (PMID 27733900, 2016). "In soft tissue sarcomas, PSME1 protein expression was found in the majority of the cases, both in the nucleus as well as in the cytoplasm." (PMID 27733900, 2016).
thyroid cancer (1 paper, 2025). "We used LASSO Cox regression to construct a model for the evaluation of thyroid cancer prognosis, and a risk model consisting of six genes (ACSL5, HSD17B11, CCL5, NCF2, PSME1, and ACTB) was subsequently developed." (PMID 40299520, 2025). "Given the key role of PSME1 in protein degradation and antigen presentation, its abnormal expression may affect the biological behaviour and immune evasion ability of thyroid cancer cells." (PMID 40299520, 2025).